BRCA1 (BRCA1 DNA repair associated)
Diseases named in the same sentence as BRCA1 in open-access papers (continued):
Sharing a sentence is not in itself a finding about the gene and the disease.
cancer (continued). "This implies that next to being involved in early BRCA mutation-related carcinogenesis, hypoxia and HIF-1α overexpression may also be a driver of cancer progression, especially in BRCA1 mutation carriers." (PMID 23409121, 2013). "In the future it would be very interesting to screen different human cancers for additional WDR48 mutations that might not only be defective in maintaining PHLPP1 function but also other substrates such as BRCA1, FANCD2, H2A/H2B, PCNA, and notch receptor." (PMID 24145035, 2013). "Interestingly, its “sibling” sub-genotype, het-norm/high, is associated with highest FOR at very advanced female ages, and is practically protective of autoimmune and BRCA1/2-associated cancer risks." (PMID 23948096, 2013). "Moreover, the idea that BRCA1 deficiency causes cancer solely due to genomic instability associated with the loss of HDR and cell cycle checkpoints does not account for the limited spectrum of tumor types observed in BRCA1-mutation carriers." (PMID 23802008, 2013). "It is expected that BRCA1 also mediates an ovary-specific function that could explain why the ovary is a preferred site for cancer development in women who carry BRCA1 mutations." (PMID 23802008, 2013). "Additional genes identified here are implicated in functions unrelated to BRCA1 and may constitute some new avenues to explore, leading to new therapeutic targets for BRCA1-deficient cancers." (PMID 23805307, 2013). "Recently, next generation (exome) sequencing of 316 OC revealed that over 20 percent of these cancers carried either somatic or germline inactivating mutations in either BRCA1 or BRCA2, thus emphasizing the importance of these two genes in the pathogenesis of OC." (PMID 23522120, 2013). "Similarly inherited mutations in BRCA1/2 genes predispose to cancers of the breast, ovary and prostate and to a lesser extent pancreas and colon but not lung or bone." (PMID 23907184, 2013). "The association with survival was similar in cancers with either BRCA1 or BRCA2 mutations." (PMID 24265793, 2013). "These large differences in cancer risks may have practical implications for the clinical management of BRCA1 mutation carriers, for example in deciding the timing of interventions." (PMID 23544013, 2013). "It is thought that heterozygosity status-reduced wild-type BRCA1 protein dosage (haploinsufficiency) and/or the presence of a mutant BRCA1 protein may affect BRCA1 functions and heighten the risk of cancer promoting mutations." (PMID 24223121, 2013). "In BRCA1-deficient or BRCA1-mutant cancer cells, however, the loss or mutation of BRCA1 resulted in miR-155 upregulation, since HDAC2 could not be recruited to the miR-155 promoter." (PMID 24261995, 2013). "But as the women included in this multicenter study were recruited just before the consultation at which they received their test results, our sample can be said to be a non-selected sample representative of the healthy women tested for BRCA1/2 mutations at French cancer genetic clinics." (PMID 23680028, 2013). "Although it has been known for 30 years that Parp inhibition potentiates alkylation-induced toxicity, the recent discovery of synthetic lethality in BRCA1/2 homologous recombination-deficient tumors upon Parp inhibition has renewed intense interest in using PARP inhibitors for cancer chemotherapy." (PMID 23593019, 2013). "Similarly, BRCA1 mutations predispose specifically to breast and ovarian cancer and hypermethylation is limited to cancer of these tissues." (PMID 23341493, 2013).
cancer (continued). "In addition, cancer-predisposing mutations in BRCA1 have been observed to abrogate ERα ubiquitination." (PMID 23203101, 2012). "We therefore propose that chemotherapeutical targeting of BRCA1-IRIS might be beneficial in eradicating BRCA1/p220-associated or TN/BL tumors cancer diseases." (PMID 22431556, 2012). "Identifying racial differences in genetic or lifestyle factors, which may modify the cancer risk of BRCA1/2 mutations, is also a priority for future research." (PMID 22382806, 2012). "Germline mutations of BRCA1 are also associated with this type of cancer at a high rate." (PMID 24213462, 2012). "It is therefore possible that fluctuations in different signaling pathways, or in the expression of binding partners, will influence BRCA1 nuclear import, and indeed the targeting of protein import has been linked to disease and pathological conditions such as cancer." (PMID 24278741, 2012). "If confirmed in other studies, this information may be useful for timing of risk reducing surgery in healthy BRCA1 mutation carriers, as the age at onset in index cancer cases has been found to predict individual risk." (PMID 23039163, 2012). "Three domains of the BRCA1 protein are mutated in cancer patients with relatively high frequency." (PMID 22737296, 2012). "Among carriers of BRCA1 mutations, there is significant variability in the age of onset of cancer." (PMID 22347400, 2012). "Contradicting this hypothesis is the observation that somatic BRCA1 mutations are exceedingly rare in sporadic carcinomas." (PMID 22347400, 2012). "Parallel to FA, we hypothesized that germline mutations or common variants in MORF4L1 may confer moderate/low risk of BrCa and/or modify cancer risk among BRCA1 and/or BRCA2 mutation carriers." (PMID 21466675, 2011). "Furthermore, high dose therapy is likely to counteract tumor adaptation to the drugs, e.g. to induce rapid killing of cancer cells and therefore decrease the probability of developing secondary BRCA1-restoring mutations." (PMID 21819606, 2011). "This synthetic lethality interaction led us to hypothesise that SNPs in genes participating in this pathway could be potential modifiers of cancer risk in BRCA1 and BRCA2 mutation carriers." (PMID 21427728, 2011). "This suggests that BRCA1 downregulation in sporadic cancer may also lead to a block in stem cell differentiation with the attendant increase in cancer risk." (PMID 21609478, 2011). "In BRCA1-associated cancers, the homologous recombination defect renders tumours highly sensitive to chemotherapy that causes double strand breaks (DSBs) in the DNA replication phase of the cell cycle, when homologous recombination is the dominant DSB repair mechanism." (PMID 22032731, 2011). "The identification of HR defects in cancers (beyond BRCA1/2 mutations) may potentially indicate sensitivity of PARPi." (PMID 21989215, 2011). "Many women fear that BRCA1/2-associated cancers are more aggressive than are sporadic tumors." (PMID 22295226, 2011). "Results of biomarker studies were available for most of the BRCA1-associated cancers." (PMID 21080930, 2010). "This may mean that the tested family member developed cancer by chance, or there is a very small chance that a mutation is present in BRCA1 or BRCA2 but was missed due to limitations in current technology." (PMID 20180951, 2010). "For example, secondary mutations of BRCA1 or BRCA2 (essential factors in the HR pathway) caused by chemotherapy using cisplatin or poly(ADP-ribose) polymerase inhibitor in BRCA1/2-mutated cancers restore the wild-type reading frame and, therefore, the tumor acquires resistance to these drugs." (PMID 20205718, 2010). "Based on the available literature, it is deemed appropriate to acknowledge that the clinical management of cancer risk in BRCA1 and BRCA2 mutation carriers is a rather complex and stressful task, which should consider individual patients' expectations and preferences." (PMID 20961453, 2010).
cancer (continued). "Our comparison of the pathologic features of ER+ and ER- BRCA1 cancers revealed that the ER+ cancers less often had features typically associated with BRCA1 cancers, such as high mitotic rate, pushing margins, marked lymphocytic infiltrate, and geographic necrosis/fibrotic focus." (PMID 20149218, 2010). "However, none of these studies was designed to specifically evaluate loss of wt BRCA1 in relation to ER status in BRCA1-associated cancers." (PMID 21080930, 2010). "Another recent study has found expansion of a committed luminal progenitor population, containing both ER+ and ER- cells, in preneoplastic tissues of BRCA1 mutation carriers and proposed the luminal progenitor cells as the cell of origin of BRCA1-associated cancers." (PMID 21080930, 2010). "Our results suggest that the high grade ER+ luminal cancers also may be enriched for tumors with BRCA1 or BRCA2 deficiency." (PMID 21080930, 2010). "However, despite prophylactic measures to reduce risk of EOC, many BRCA1/2 carriers will already have cancer at the time their mutation is diagnosed." (PMID 20049345, 2010). "Fifty-nine cancers occurred in women with a small BRCA1 insertion or deletion mutation, four additional women had a large 40 base-pair deletion (1294del40), seven had nonsense point mutations and three had a splice site mutation resulting in an in-frame deletion of an exon." (PMID 21080930, 2010). "In the last few years, the identification of individuals carriers of inactivating mutations on BRCA1 and 2 genes has been essentially directed to cancer prevention by the use of prophylactic surgery, preventive treatments or screening procedures different from general population." (PMID 19825178, 2009). "Cancer risk associated with BRCA1 mutation can thus be explained by two models." (PMID 19352458, 2009). "Furthermore, the proportion of BRCA1-associated cancers that are ER-negative (one of the component features) diminishes with increasing age-of-onset." (PMID 19298662, 2009). "Cancers in BRCA1 and BRCA2 mutation carriers have substantial difference between them." (PMID 19226467, 2009). "Regardless of the mechanism, our findings have important ramifications regarding the design of future studies for the estimation of cancer risks and more specifically on the counselling of patients with BRCA1 mutations, in that the mutation type should be included in risk calculations." (PMID 19329713, 2009). "In the under 51 years old they found a much larger fraction of patients harboring MDM2 SNP309G/G compared to the fraction of patients harbouring this SNP in the over 51 years old, supporting a role for this SNP as a modifier of cancer risk in BRCA1/2 mutation carriers." (PMID 19226467, 2009). "Moreover, the significant higher levels of XIST-RNA detected in BRCA1-associated respect to sporadic basal-like cancers, opens the possibility to use XIST expression as a marker to discriminate between the two groups of tumors." (PMID 19440381, 2009). "Importantly, we show that BRCA1-deficient cancer cells are selectively dependent on their elevated EZH2 levels." (PMID 19709408, 2009). "Very little is known about the effects of BRCA1/2 mutations on phenotypes other than cancer." (PMID 19277124, 2009). "BRCA1 has been shown to directly interact with IGF signaling such that variants in this pathway may modify risk of cancer in women carrying BRCA mutations." (PMID 19843326, 2009). "However, 28% of subjects underwent the procedure in the operating room under general anesthesia and less than one percent of the subjects were cancer-unaffected, known BRCA1/2 mutation carriers." (PMID 19602282, 2009). "In the last decade, several reports have been published supporting the hypothesis that different mutations in the BRCA1 or BRCA2 genes confer different cancer-related risks." (PMID 19329713, 2009). "Interestingly, our data confirm that the incidence of BRCA1 mutations in the ER and/or PR positive cancers is low." (PMID 19818148, 2009).
cancer (continued). "Although BRCA1 is involved in a large number of cellular processes, it is the maintenance of genomic stability that has been proposed to be the principal factor underlying cancer predisposition in mutation carriers." (PMID 19165203, 2009). "In the current study we analyzed the relationship between MDM2 309 SNP status and cancer in a large group of Ashkenazi patients including a large group of BRCA1/2 mutation carriers Our results revealed high percentage of MDM2 309 SNP in this population of around a quarter of all women." (PMID 19226467, 2009). "The GEMO study (Genetic Modifiers of cancer risk in BRCA1/2 mutation carriers): Cancer Genetics Network ‘Groupe Génétique et Cancer’, Fédération Nationale des Centres de Lutte Contre le Cancer, France): We thank all the GEMO collaborating members for their contribution to this study." (PMID 19920816, 2009). "Cancer risks associated with BRCA1 and BRCA2 mutations have been well documented, but are varied." (PMID 19102775, 2008). "Variation in penetrance estimates for BRCA1/2 carriers suggests that other environmental and genetic factors may modify cancer risk in carriers." (PMID 18542066, 2008). "In fact, the analysis of only 4 PCR fragments (1806C>T, exon 5 (300T>G, 300T>A), 5382insC in the BRCA1 gene and IVS16-2A>G in the BRCA2 gene) would lead to the identification of the cancer predisposing mutations in 67% of the BRCA1/2 mutation-positive families." (PMID 18783588, 2008). "The original and transplanted tumors as well as well-characterized cell lines derived from original tumors provide the necessary tools for studying the biology of Brca1-deficient tumors, identification of putative cancer stem cells, and development of novel therapies to improve clinical outcome." (PMID 18394172, 2008). "In addition, many Brca1- and Brca2-deficient mouse models with cancer susceptibility have been generated." (PMID 18047734, 2007). "Our results suggest that, of the recurrent alterations described for BRCA1-associated and high-grade carcinomas, some could be specific for the basal-like spectrum of tumors." (PMID 17417968, 2007). "The distinctive evolution of human and chimpanzee BRCA1 suggest that an evolutionary approach may be important to understanding selection at this, and perhaps other cancer associated genes." (PMID 16438707, 2006). "Finally, Brekelmans, who has enrolled 1198 women characterized by BRCA1/2 mutations or by a BC risk over 15% between 21–70 years of age in a screening program, found 35 cancers (31 invasive and 4 DCIS) after a median follow-up of 3 years." (PMID 16916448, 2006). "There is nonetheless evidence from BRCA1 mutation carriers that TAM may be effective in long-term prevention of second primary cancers and part of this is likely to be due to a primary preventive role." (PMID 16538216, 2006). "We assumed that if tamoxifen was equally effective in reducing ER- and ER+ cancers, the risk reduction might approximate that seen following oophorectomy in women with inherited mutations in BRCA1/2." (PMID 16457695, 2005). "Given that BRCA1 sequencing (and thus variant identification) is generally undertaken in individuals with cancer or with a family history of cancer, it is assumed that the majority of these variants were identified in such individuals, and that at least a fraction of them predispose to cancer." (PMID 16280041, 2005). "Participants are adults unaffected with cancer from families with a known BRCA1/2 mutation." (PMID 11953874, 2002). "Similarly, other cancers are over-represented providing additional evidence that BRCA2 mutations result in a less restricted disease phenotype than BRCA1 mutations." (PMID 12373604, 2002). "bcl-2 might thus be one of the target genes involved in the oncogenesis related to Brca1 and its down-regulation may account for the increased apoptosis and the high proliferative rate observed in Brca1 -associated carcinomas." (PMID 11044356, 2000).
cancer (continued). "However, the concept gained traction in cancer therapy when researchers recognized that cancer cells, particularly those with certain gene mutations such as BRCA1 and BRCA2, could be selectively targeted using specific inhibitors." (PMID 40450009, 2025). "An example may be the use of poly (ADP-ribose) polymerase (PARP) inhibitors (PARPis), drugs with already proven effectiveness in humans, for treatment of patients with DNA damage repair-deficient cancers, mainly with Breast Cancer Associated 1 and 2 (BRCA1 and BRCA2) mutations." (PMID 40616061, 2025). "BRCA1 mutations may also be associated with responses to chemotherapy and cancer survival." (PMID 40361383, 2025). "Furthermore, our findings indicate that the genetic status and protein levels of TLK could serve as potential biomarkers for resistance or sensitivity to PARPi therapy in BRCA1-mutated cancer cells." (PMID 39844055, 2025). "BRCA1-deficient cancers may develop and advance due to microenvironmental changes." (PMID 40584290, 2025). "Therefore, we assessed whether cell line collections with a BRCA1/2 mutation recapitulate this response observed in the clinic by analysing synergy data from the Genomics Drug Sensitivity in Cancer drug combination database (GDSC; Wellcome Sanger Institute)." (PMID 40977519, 2025). "Consequently, these findings further emphasise the mitotic CIP2A-TOPBP1 axis as a promising therapeutic target in BRCA1/2-deficient cancers and those with elevated DNA replication stress, while highlighting actionable avenues for anti-cancer therapy development." (PMID 41309571, 2025). "Notably, the downregulation of TLK may be exploited by cancer cells as a mechanism of resistance to PARPi, even in the context of BRCA1 mutation." (PMID 39844055, 2025). "In addition, we observed that these organoids contain outgrowths that resemble the mature ductal and lobular units of the mammary gland, thus making it a suitable model system to study how cancer develops in ER/PR/HER2-negative mammary cells that carry a BRCA1 germline mutation." (PMID 41283387, 2025). "Similarly, olaparib-induced TIS in BRCA1-deficient cancer cells—a model of transient, unprimed senescence—shows remarkable sensitivity to A1331852, further highlighting the versatility of BCL-xL-targeted senolytics against mechanistically heterogeneous TIS states." (PMID 40055336, 2025). "Alteration of the natural ratio between BRCA1 isoforms could be involved in cancer predisposition." (PMID 39980563, 2025). "Therefore, we hypothesize that combining PARP and DNA-PK inhibitors could synergistically eliminate BRCA1/2-deficient cancer cells." (PMID 41236806, 2025). "Moreover, the survival of BRCA1- or ATM-deficient cancer patients could be triaged by SETD1A expression, which was not the case for those with deficiencies in BRCA2, nor those with functional copies/levels of these genes." (PMID 39994444, 2025). "Indeed, our data show that RAD18 recruitment to chromatin upon HU treatment depends on RFN168 in BRCA1-deficient cancer cells, indicating that RNF168 might act upstream of RAD18 to facilitate its recruitment to degraded forks and fork recovery." (PMID 38943334, 2024).